INS (insulin)
Diseases named in the same sentence as INS in open-access papers (continued):
Sharing a sentence is not in itself a finding about the gene and the disease.
Hypoglycemia (continued). "In all patients who have recurrent episodes of hypoglycemia during weaning from parenteral nutrition, or higher than normal glucose requirements to maintain euglycemia (>8 mg/kg/min), evaluation of insulin concentrations at the time of hypoglycemia is mandatory." (PMID 37929024, 2023). "Moreover, icodec and Basal Insulin Fc did not result in higher incidence of hypoglycemia compared with insulin daily." (PMID 38206709, 2023). "However, no hypoglycemia was observed in rats treated with conventional vesicles, suggesting the importance of sodium cholate in promoting transdermal insulin delivery." (PMID 36979643, 2023). "In the case of insulin, an injection at too high a dose, e.g., due to non-adherence with mealtimes or prescription errors, this may result in severe hypoglycemia, often requiring hospitalization." (PMID 37770912, 2023). "Insulin is not preferable for use in children because of its major adverse effect (hypoglycemia)." (PMID 37628380, 2023). "However, they found a significant decrease in nocturnal hypoglycemia from the baseline with insulin degludec but not with insulin glargine." (PMID 36800034, 2023). "Such functional dichotomy may help explain observations that hypoglycemia unawareness can be reversed in insulin-dependent diabetics without effectively reversing impaired glucose counterregulation." (PMID 37048567, 2023). "We are not able to evaluate if disturbances in the early/late insulin response may play a role, but relatively high and sustained insulin secretion might explain delayed hypoglycemia in FA and BED." (PMID 37726785, 2023). "Several studies from Saudi Arabia have enumerated various factors affecting adherence to the treatment of DM, including male gender, fear of injection, fear of hypoglycemia, injection site reactions, and poor self-administration technique of insulin due to the lack of adequate knowledge." (PMID 37240580, 2023). "For adolescents, at M12, there were no episodes of hypoglycaemia during insulin pump treatment." (PMID 37185052, 2023). "Of note, too much insulin release leading to hypoglycemia is not desirable." (PMID 37264038, 2023). "This nationwide cohort study showed that patients with T2D and COPD requiring insulin therapy may have an increased risk of acute COPD exacerbations, pneumonia, ventilator use, and severe hypoglycemia without a significant increase in the risk of death." (PMID 37242426, 2023). "IAs could prevent insulin from binding its receptor, possibly resulting in the deterioration of the physiological effects of insulin; thereafter, insulin is released from the complexes irrespective of blood glucose concentrations, thus inducing hypoglycemia." (PMID 37324170, 2023). "indicate that insulin analog initiation therapy activates lipid metabolism via up-regulating cholesteryl ester transfer protein (CETP) and can increase HDL levels.In patients with insulinoma, islet cells can continuously secrete a large amount of insulin, resulting in hypoglycemia." (PMID 37033225, 2023). "Across all three insulin-requiring Igls groups, most recipients self-reported unresolved impairment in hypoglycaemia awareness without significant differences in Gold or HypoA-Q “Impaired Awareness” scores in those with “Good,” “Marginal” or “Failed” graft function." (PMID 37822448, 2023). "Without restoring glucagon counterregulation to hypoglycemia in T1D and advanced T2D, strategies for improving glycemic control, including the use of newer insulin analogues and continuous glucose monitoring, fail to eliminate the risk of clinically significant hypoglycemia." (PMID 38298268, 2023). "In the setting of intensive glycemic control achieved with intensive insulin delivery, complete avoidance of hypoglycemia may not be realistic for some individuals." (PMID 37942482, 2023).
Hypoglycemia (continued). "However, no discernible difference was found between the MDI and continuous subcutaneous insulin infusion (CSII) group in terms of HbA1c, the proportion of hypoglycemia events, and insulin dose (7.42 ± 0.74 vs 7.49 ± 0.84%, 59.1 vs 57.1% and 0.49 ± 0.20 vs 0.44 ± 14 units/kg/day, P > 0.05)." (PMID 36860372, 2023). "Furthermore, delayed beta-cell insulin secretion rather than alpha cell dysfunction likely explains the occurrence of post-oral glucose challenge hypoglycaemia seen early in the development of glucose intolerance in CF." (PMID 37720541, 2023). "Symptoms of hypoglycaemia may be more prevalent in patients on insulin; however, in this study, the score for this subscale was not significant." (PMID 38213386, 2023). "Similarly, a study examining Semaglutide yielded a similar conclusion, observing a non-increased incidence of hypoglycemia vs. sitagliptin, exenatide or insulin." (PMID 37349787, 2023). "Their mechanisms of action may have a role to play as no other antidiabetic medications directly interact with insulin, including SGLT2-Is, and do not pose as great of a risk for hypoglycemia." (PMID 37180737, 2023). "The sustainability and maintenance of insulin secretion following OSA® exposure may provide therapeutic benefits in long-term glycemic control and thus reduce dosing frequency, although careful dosage would be needed to avoid potential hypoglycemia." (PMID 38202777, 2023). "In clinical situations where insulin management is based on patient-generated home glucose data, and HbA1c is not available at the time of clinic visit, AH patients did not have the occurrence of hypoglycemia higher than W patients." (PMID 38706529, 2023). "Combining a DPP-4 inhibitor with insulin therapy may be useful in patients with T2DM for improving glucose control without prompting hypoglycaemia and likely suitable for restricting weight gain." (PMID 37287751, 2023). "In addition, hypoglycaemia seemed to be explained by a temporal mismatch between glucose and insulin levels rather than by an impaired glucagon response." (PMID 37720541, 2023). "This single-arm longitudinal intervention study showed that a healthcare professional supported 12-week LC diet (25–75 g/day) improved markers of blood glucose control and quality of life with reduced total daily insulin dosages and no reported episodes of ketoacidosis or severe hypoglycaemia." (PMID 37432920, 2023). "Evidence suggests that hypoglycemia is more common in individuals treated with premixed and bolus, and weight gain is more common in those treated with bolus; while in patients treated with BOT, fewer adverse effects were observed compared with those treated with premixed or bolus insulin." (PMID 36624650, 2023). "The decrease in non-severe hypoglycaemia in T2DM outpatients may be explained by less of a use of insulin therapy or less stringent target ranges for glycaemic control." (PMID 36768000, 2023). "In level 1 hypoglycemia, level 2 or 3 hypoglycemia, injection-site reaction, hypersensitivity event, and any adverse event probably or possibly related to basal insulin, there was no statistical difference between Icodec and once-daily insulin." (PMID 38206709, 2023). "In addition, continuous subcutaneous insulin infusion with a pump resulted in a greater reduction in glycated hemoglobin without a higher rate of hypoglycemia compared with multiple daily insulin injections." (PMID 40838053, 2023). "People who produce an adequate amount of their own insulin may benefit more from taking one of several oral medications that do not result in hypoglycemia when administered alone." (PMID 38132485, 2023). "However, a direct effect of insulin and/or insulin‐induced hypoglycaemia on CBC activity is not established in animal models." (PMID 36459572, 2023). "Furthermore, information regarding other glucose-related factors like diabetic drugs, history of severe hypoglycemia, and levels of insulin was not available." (PMID 37891651, 2023).
Hypoglycemia (continued). "A predecessor device was evaluated in the TeleDiab-2 randomized controlled trial, showing that a higher percentage of patients using the app achieved their target fasting blood glucose (FBG) level compared to the control group, and insulin doses were adjusted to higher levels without hypoglycemia." (PMID 36749650, 2023). "In conclusion, in patients with type 1 and type 2 DM, switching to insulin degludec offered better glycemic control, which was manifested by a reduction in HbA1c levels, a reduction in insulin dose, and no increase in the frequency of reported hypoglycemia in this Saudi Arabian population." (PMID 36601214, 2023). "Interestingly, they also observed that for patients not being treated with insulin, the link between hypoglycemia and mortality was increased, and the time to death was shorter compared to those receiving insulin." (PMID 36675389, 2023). "In addition, patients not using diabetes medications or insulin generally do not present with hypoglycemia, making it difficult for healthcare providers to suspect hypoglycemia." (PMID 38868726, 2023). "In the MiTy study, the primary composite outcome of neonatal mortality and morbidity (comprising pregnancy loss, preterm birth, birth injury, respiratory distress, neonatal hypoglycemia, and admission to intensive care for > 1 day) was similar with or without metformin added to the insulin." (PMID 37401946, 2023). "Mini-glucagon 19-29 has a potent limiting effect on insulin secretion and it could happen that RYGB modifies the released ratios of glucagon/mini-glucagon 19-29, which could explain the episodes of postprandial hypoglycemia." (PMID 37635984, 2023). "The effect of elevated insulin sensitivity is clearly visible as the BG trajectories stay separated for the remaining simulation time, and results suggest that no additional adjustments are necessary to protect against hypoglycemia for exercise up to an hour." (PMID 36791144, 2023). "Moreover, the GINGER study showed superior glycemic control without an increase in hypoglycemia using insulin Gla-100 than premixed insulin in patients with long-standing T2DM." (PMID 36624650, 2023). "However, insulin therapy has several disadvantages, including the need for multiple injections, risks of hypoglycemia and hyperbilirubinemia, the rising cost of insulin, and the lack of affordability." (PMID 36593391, 2023). "Furthermore, there are isolated cases of non-diabetic youth with doxycycline-induced hypoglycemia, which is compatible with the increase in serum insulin generated due to doxycycline." (PMID 36979696, 2023). "To understand the effects of acute insulin‐induced hypoglycaemia on carotid chemoreceptor sensitivity and cardiorespiratory responses, we compared the NaCN‐mediated CSN neurogram and cardiorespiratory reflex responses during euglycaemia and after insulin‐induced hypoglycaemia." (PMID 36459572, 2023). "Insulin dose reduction may prevent hypoglycemic events, and rapid-acting insulin analogs may improve glycemic control without incurring subsequent hypoglycemia during Ramadan." (PMID 35634376, 2022). "When deprescribing, professionals may not only consider the reduction of insulin doses and the simplification of complex insulin regimes but also stopping sulfonylurea treatment and starting an antidiabetic that does not induce hypoglycemia." (PMID 36079064, 2022). "As RT2;B6 mice usually die from hypoglycemia due to functional PanNET and not from tumor burden, we asked whether blood insulin and glucose were stabilized by treatment." (PMID 35118189, 2022). "This study found that the insulin surge following the meal was blunted with the administration of the GLP-1 antagonist, suggesting that GLP-1 plays an important role in the exaggerated insulin response seen in post-prandial hypoglycemia in children who had undergone a fundoplication." (PMID 35399928, 2022).
Hypoglycemia (continued). "Given the seriousness and the apparent high frequency of hypoglycaemia following insulin therapy, and the fact that this has not been comprehensively studied, we conducted a scoping review of this important complication, and of other adverse effects of the treatment of hyperkalaemia." (PMID 35552566, 2022). "Thus, the elevation of both insulin and glucagon after GPR40 activation may be a mechanism to harmonize between the uptake of energy in the forms of FFAs and the prevention of hypoglycemia under the intake of HFD." (PMID 36246919, 2022). "Therefore, patients who are capable of self-monitoring blood glucose to avert the negative effects like hypoglycemia would be better to initiate with premixed insulin regimens." (PMID 36149907, 2022). "Conversely, during low blood glucose conditions (hypoglycemia), insulin is not required, and the hydrogels may control and stop insulin delivery." (PMID 36072265, 2022). "Of the remaining 36 cats that received insulin and dextrose, five were lacking BG data (two had no BG measured for the visit and three had only a presentation BG but none recorded following insulin administration) and were therefore excluded from analysis regarding development of hypoglycemia." (PMID 36350735, 2022). "The LIGHTNING study reported significantly lower severe hypoglycaemia event rates for Gla‐300 versus IDet (but not Gla‐100) among patients with renal impairment, prandial insulin and aged ≥65 years, but not recent hypoglycaemia (using similar definitions to the current study)." (PMID 34807513, 2022). "c-peptide levels were generally < LLOQ in these animals at this time-point, however, it could suggest that insulin production is slowly recovering, but insulin is not secreted due to the negative feed-back of the hypoglycaemia." (PMID 35982111, 2022). "Of the six cats that developed hypoglycemia within 6 h, four (67%) had received a dextrose CRI from the time of insulin administration; of the two cats that developed hypoglycemia between 6 and 12 h, one received a dextrose CRI starting at the time insulin was given." (PMID 36350735, 2022). "Incidence of hypoglycemia events (glycemia < 70 mg/dL) and severe hypoglycemia (glycemia < 40 mg/dL); median total daily dose of correcting insulin and number of patients in use of basal insulin during hospital stay were not significantly different between groups." (PMID 36233642, 2022). "However, there was no available predictive score to predict hypoglycemia after treating hyperkalemia with insulin and glucose." (PMID 36371171, 2022). "In this study, however, insulin supplementation did not prevent attenuation of the corticosterone counterregulatory response, suggesting differential effects of recurrent hypoglycemia on hypothalamo-pituitary axis function and sympathoadrenal counterregulation." (PMID 36676967, 2022). "Consequently, a 72-h fasting test was initiated and had to be stopped after 4 h due to hypoglycemia (16 mg/dL) with increased insulin and C-peptide levels (data not shown)." (PMID 35406570, 2022). "In CVOTs, the incidence of hypoglycemia was not increased with empagliflozin, canagliflozin, or dapagliflozin compared with placebo, despite approximately half the patients receiving concomitant insulin." (PMID 36294370, 2022). "However, insulin infusion is not free from serious complications, including hypoglycemia, that remains an important and risky possible consequence." (PMID 35135591, 2022). "A subsequent review study showed that the rates of severe hypoglycemia in T2D were between 0.7 and 12 per 100 person-years in randomized controlled trials and between 0.2 (without treatment with insulin or sulfonylureas) and 2 (with treatment with insulin or sulfonylureas) per 100 person-years." (PMID 35576579, 2022).
Hypoglycemia (continued). "Episodes of SH were reported by 251 (19%) individuals who, compared with subjects with nonsevere hypoglycemia, received lower doses of prandial insulin and higher doses of basal insulin, in addition to reporting less frequent use of long-acting basal insulin analogs." (PMID 36191264, 2022). "Given the low numbers (n = 8) of cats that could be evaluated for the development of hypoglycemia, meaningful statistical analyses could not be performed regarding a dextrose:insulin ratio that protected against evolution of hypoglycemia." (PMID 36350735, 2022). "Moreover, with or without insulin, some patients suffered hypoglycemia, with an incidence of 12.9% (16/124) in the insulin group and 0.4% (14/235) in the noninsulin group." (PMID 35237639, 2022). "However, we must note that during the analyzed period, the time below range increased, indicating the need to adjust insulin dosing so as to not overtreat diabetic patients, as hypoglycemia also negatively affects prognoses." (PMID 35215390, 2022). "Because STZ-diabetic keto-fed rats displayed comparable baseline BG concentrations to the STZ-diabetic insulin-supplemented chow fed rats, both cohorts were subjected to the single or recurrent hypoglycemia protocols without further subdivision into hyperglycemic and normoglycemic groups." (PMID 36676967, 2022). "Interestingly, despite the severe impairment in glucose sensing and glucagon secretion, this did not result in severe hypoglycaemia in gluACC1KO mice (relative to controls) after fasting or insulin injection." (PMID 35304577, 2022). "Administration of Glulisine along with the Glargine insulin fifteen minutes before the meal revealed considerably more decline in HbA1c as opposed to that by human regular insulin subjected 30–45 min before meals, while evidence of acute hypoglycemia was equivalent." (PMID 35723344, 2022). "Additionally, declined probability of hypoglycemia, higher satisfaction, and in certain cases, low weightage represent the advantages facilitated by insulin preparations as opposed to human insulin." (PMID 35723344, 2022). "Most previous randomized studies reported the superiority of insulin combined with metformin in reducing HbA1c, weight gain, insulin dose or hypoglycemia compared with insulin alone or insulin plus other OADs, whereas they were not always concordant with each other." (PMID 35045841, 2022). "Closed-loop insulin delivery systems were not available to participants at recruitment but those of its component technologies with proven benefit on severe hypoglycaemia (continuous glucose monitoring and automated suspension of insulin delivery) were available." (PMID 35484106, 2022). "Due to the risks of hypoglycemia and weight gain, no studies have investigated the hypotheses that experimentally controlled, long-term exogenous insulin treatment engenders PCOS in healthy women, and/or amplifies the severity of PCOS phenotypic expression." (PMID 35269778, 2022). "A study that only monitored for 60 minutes following insulin reported no episodes of hypoglycaemia." (PMID 35552566, 2022). "Even when youth develop T1D, their glucagon release in response to hypoglycemia appears to be altered early after onset (the first year), and adults with T1D who have continued to make small amounts of their own insulin also have impaired and/or absent glucagon release when hypoglycemia occurs." (PMID 36992764, 2022). "However, about half of them admitted that fear of insulin-induced hypoglycemia (46.5%) and lack of staff for patient training and education (49.3%) were the main barriers that made them reluctant to prescribe insulin for T2D patients." (PMID 36554673, 2022). "In this previous study, HbA1c decreased more, less time was spent in hypoglycemia, and insulin pump was used more frequently when real-time data were available to the subjects compared with those during blinded CGM in patients with type 1 diabetes (T1DM) using insulin pump therapy." (PMID 35222287, 2022).